RAB3A (RAB3A, member RAS oncogene family)
Description:
The small GTPases Rab are key regulators of intracellular membrane trafficking, from the formation of transport vesicles to their fusion with membranes. Rabs cycle between an inactive GDP-bound form and an active GTP-bound form that is able to recruit to membranes different sets of downstream effectors directly responsible for vesicle formation, movement, tethering and fusion. RAB3A plays a central role in regulated exocytosis and secretion. Controls the recruitment, tethering and docking of secretory vesicles to the plasma membrane. Upon stimulation, switches to its active GTP-bound form, cycles to vesicles and recruits effectors such as RIMS1, RIMS2, Rabphilin-3A/RPH3A, RPH3AL or SYTL4 to help the docking of vesicules onto the plasma membrane (By similarity). Upon GTP hydrolysis by GTPase-activating protein, dissociates from the vesicle membrane allowing the exocytosis to proceed (By similarity). Stimulates insulin secretion through interaction with RIMS2 or RPH3AL effectors in pancreatic beta cells (By similarity). Regulates calcium-dependent lysosome exocytosis and plasma membrane repair (PMR) via the interaction with 2 effectors, SYTL4 and myosin-9/MYH9. Acts as a positive regulator of acrosome content secretion in sperm cells by interacting with RIMS1. Also plays a role in the regulation of dopamine release by interacting with synaptotagmin I/SYT (By similarity).
Synonyms: SCA52
Tractability: Antibody: UniProt places it where antibodies can reach, with high confidence; its Gene Ontology location is reachable by antibodies, with high confidence. PROTAC: ubiquitination databases record sites on it; its protein half-life has been measured.
Gene: Protein-coding gene on chromosome 19 (18,196,752 to 18,204,042, reverse strand). Ensembl gene ENSG00000105649.
Subcellular location: Cytoplasm, cytosol; Lysosome; Cytoplasmic vesicle, secretory vesicle; Cell projection, axon; Cell membrane; Presynapse; Postsynapse
Subcellular location (Human Protein Atlas): Nucleoplasm; Centrosome; Cytosol
Pathways (Reactome):
Neuronal System: Acetylcholine Neurotransmitter Release Cycle; Dopamine Neurotransmitter Release Cycle; GABA synthesis, release, reuptake and degradation; Glutamate Neurotransmitter Release Cycle; Norepinephrine Neurotransmitter Release Cycle; Serotonin Neurotransmitter Release Cycle
Immune System: Neutrophil degranulation
Metabolism of proteins: RAB geranylgeranylation
Sensory Perception: Sensory processing of sound by inner hair cells of the cochlea
Vesicle-mediated transport: RAB GEFs exchange GTP for GDP on RABs
Gene Ontology:
Molecular function: G protein activity; GTPase activity; myosin V binding; protein binding; GTP binding; GTP-dependent protein binding; protein-macromolecule adaptor activity
Biological process: acrosomal vesicle exocytosis; exocytosis; lysosome localization; plasma membrane repair; positive regulation of regulated secretory pathway; regulated exocytosis; regulation of plasma membrane repair; axonogenesis; constitutive secretory pathway; positive regulation of exocytosis; regulation of short-term neuronal synaptic plasticity; regulation of synaptic vesicle fusion to presynaptic active zone membrane; synaptic vesicle exocytosis; synaptic vesicle recycling; calcium-ion regulated exocytosis; evoked neurotransmitter secretion; insulin secretion; regulation of presynaptic dense core granule exocytosis; synaptic vesicle clustering; synaptic vesicle transport
Cellular component: extracellular vesicle; lysosome; perinuclear region of cytoplasm; axon; clathrin-sculpted acetylcholine transport vesicle membrane; clathrin-sculpted gamma-aminobutyric acid transport vesicle membrane; clathrin-sculpted glutamate transport vesicle membrane; clathrin-sculpted monoamine transport vesicle membrane; cytosol; endosome; plasma membrane; postsynapse; presynapse; presynaptic active zone; secretory granule membrane; synaptic vesicle; synaptic vesicle membrane; terminal bouton; acrosomal vesicle; transport vesicle; vesicle
Genetic constraint (gnomAD): Loss-of-function variants: 5 observed, 22.17 expected, observed/expected ratio (o/e) 0.23, 90% interval 0.12 to 0.47. The upper end of that interval is the gene's LOEUF score, 0.47, which puts it in group 2 of 6, group 1 being the genes least tolerant of losing a copy. Missense variants: 189 observed, 319.79 expected, observed/expected ratio (o/e) 0.59, 90% interval 0.52 to 0.67. Synonymous variants: 119 observed, 127.76 expected, observed/expected ratio (o/e) 0.93, 90% interval 0.8 to 1.09.
Homologues: Orthologues: chimpanzee RAB3A (100% identical), macaque RAB3A (100% identical), dog RAB3A (99% identical), guinea pig RAB3A (99% identical), mouse Rab3a (99% identical), pig RAB3A (99% identical), rat Rab3a (99% identical), tropical clawed frog rab3a (98% identical), zebrafish rab3ab (94% identical), zebrafish rab3aa (87% identical). Paralogues in human: RAB3C (83% identical), RAB3B (78% identical), RAB3D (77% identical), RAB8A (47% identical), RAB8B (45% identical), RAB10 (44% identical), RAB13 (43% identical), RAB1A (42% identical), RAB12 (40% identical), RAB1B (40% identical), RAB27A (39% identical), RAB27B (39% identical), and 56 more.
Diseases named in the same sentence as RAB3A in open-access papers:
RAB3A is named in the same sentence as 58 diseases in open-access papers, as found by Europe PMC text mining. Sharing a sentence is not in itself a finding about the gene and the disease. The quoted sentences say what the papers report.
Parkinson disease (5 papers, 2013 to 2024). A progressive degenerative disorder of the central nervous system characterized by loss of dopamine producing neurons in the substantia nigra and the presence of Lewy bodies in the substantia nigra and locus coeruleus. "Additionally, one SNP is implicated in ALS, and 20 SNPs are implicated in Parkinson’s disease through meta-analyses of the RAB3A gene." (PMID 37510383, 2023). "Finally, we show that phosphorylation of a-Syn residue Ser 129, a modification associated with Parkinson’s disease pathology, enhances its interactions with Rab3a and increases its ability to inhibit Rab3a GTP hydrolysis." (PMID 35809645, 2022).
Alzheimer disease (4 papers, 2020 to 2025). A progressive, neurodegenerative disease characterized by loss of function and death of nerve cells in several areas of the brain leading to loss of cognitive function such as memory and language. "These compounds have been shown to upregulate the expression of Rab3a and SV2B proteins, restoring electrophysiological function in human embryonic stem cell-derived Alzheimer’s disease models." (PMID 40659647, 2025). "RAB3A is a small GTP-binding protein regulating synaptic vesicle exocytosis, and is reduced in the brain of patients with Alzheimer’s disease and other dementia." (PMID 34423299, 2021).
schizophrenia (4 papers, 2019 to 2023). A major psychotic disorder characterized by abnormalities in the perception or expression of reality. "Rab3A protein levels were studied twice and both times were found significantly reduced in schizophrenia." (PMID 29511299, 2019). "Both studies of Rab3A found a significant reduction in protein levels in CC in schizophrenia." (PMID 29511299, 2019).
dementia (3 papers, 2015 to 2021). Loss of intellectual abilities interfering with an individual's social and occupational functions. "aSyn associates with Rab3a, Rab5 and Rab8 in dementia with LB patients and mouse models, and an interaction between endocytosed aSyn and Rab11a has been observed in mammalian cells." (PMID 25305083, 2015).
diabetes (3 papers, 2022 to 2025). "Intracellular serotonin regulates insulin secretion from pancreatic β cells through serotonylation of GTPases (Rab3a and Rab27a), and mice selectively deficient in serotonin develop diabetes." (PMID 39926388, 2025). "Because intracellular serotonin regulates insulin secretion from pancreatic β cells through serotonylation of Rab3a and Rab27a, mice selectively deficient in serotonin develop diabetes." (PMID 39926388, 2025). "All these findings point to the Rab3A/27A system as a key participant in podocyte injury and in vesicular traffic regulation in the context of diabetes." (PMID 37237503, 2023). "Several switch genes, including AKT3, LAMA2, ADCY1, RAB3A, RAPGEF4, and ABCC8, have been implicated in insulin signaling and diabetes." (PMID 36389068, 2022).
hepatocellular carcinoma (3 papers, 2018 to 2024). A malignant tumor that arises from hepatocytes. "In Hep3B cells, hyper O-GlcNAc modification regulates Rab3A, which attenuates the tumor suppressor effect of Rab3A on hepatocellular carcinoma (HCC) metastasis." (PMID 39041003, 2024). "Although the functions of Rab3A have been reported in several cancers, the roles of Rab3A in hepatocellular carcinoma (HCC) have never been determined." (PMID 30237463, 2018). "However, the role of Rab3A in hepatocellular carcinoma (HCC) has never been determined." (PMID 30237463, 2018).
major depressive disorder (3 papers, 2017 to 2024). An episode of depression lasting two or more weeks without an intervening episode of mania. "Downregulation of synaptic genes like Syn1, Rab3a, Camk2a, Nrxn2 have been strongly associated with major depression." (PMID 29743870, 2018). "GATA1 is known to repress transcription of synaptic genes like Syn1, Camk2a, and Rab3a, and associated with Major Depressive Disorder in human patients." (PMID 29743870, 2018). "Toxic RNA foci have been demonstrated in astrocytes, cortical neurons and oligodendrocytes in hippocampus, frontal and temporal cortex, thalamus and cerebellum.RAB3A upregulation and synapsin I hyperfosforilation were linked to alteration of long-term potentiation and long-term depression." (PMID 39451985, 2024). "Rab3a is a synaptic protein that was shown to be suppressed in brain tissues from patients with major depressive disorder and stressed rats." (PMID 29375311, 2017).
Type 2 diabetes (3 papers, 2013 to 2019). "It was recently shown that the expression of multiple genes encoding components of the docking machinery, including Rab3a and Rab27a, were reduced in islets from type 2 diabetics and that the overexpression of these components could promote granule docking." (PMID 31533953, 2019). "We have previously shown that the expression of Rab3a, Rab27a and Slp4/granuphilin is altered upon exposure of β-cells to conditions mimicking those encountered in Type 2 diabetes." (PMID 23826383, 2013). "In addition, the proteomics analysis on pancreatic β-cells from type 2 diabetes patients also showed similar synchronous upregulation of Rab3A with some mitochondrial metabolism-related proteins including several COXs49." (PMID 30237463, 2018).
Anxiety (2 papers, 2007 to 2016). Intense feelings of nervousness, tension, or panic often arise in response to interpersonal stresses. "Using Rab3a knockout (−/−) and Ebd (loss-of-function)Rab3a mutant mice, a recent study has shown that Rab3a −/− micedisplay reduced cued fear conditioning, while Ebd mutants showboth reduced anxiety and cued fear conditioning, accompanied by altered hippocampal andcortical expression of Rab3a." (PMID 17502911, 2007). "Collectively, these data implicateprotein modulators of synaptic transmission (such as Rab3a) in theregulation of memory and anxiety, also enabling further dissectionof molecular domains involved in their regulation." (PMID 17502911, 2007).
Cognitive impairment (2 papers, 2012 to 2025). Abnormal cognition is characterized by deficits in thinking, reasoning, or remembering. "Dysfunction of the Rab3a recycling, thus neurotransmitter release might have an impact on the cognitive impairment observed in the sCJD." (PMID 23070823, 2012). "The dysfunction of Rab3a-mediated synaptic vesicles might contribute to the cognitive impairment of patients suffering from sCJD." (PMID 23070823, 2012).
colorectal cancer (2 papers, 2017 to 2023). A primary or metastatic malignant neoplasm that affects the colon or rectum. "For instance, RAB3A interacting protein (Rab3IP) is a Rab-specific GEF, and the activation of Rab proteins, including RAB3A and RAB8, has been considered a tumor-specific marker in colorectal cancer, gastric cancer, and pancreatic cancer." (PMID 37158817, 2023).
gastric cancer (2 papers, 2023 to 2025). A primary or metastatic malignant neoplasm involving the stomach. "In current investigation, we identify paired like homeodomain 2 (PITX2) as an essential transcriptional coordinator of lysosomal exocytosis genes MCOLN1 and RAS‐related protein Rab‐3A (RAB3A), which is linked to an adverse outcome in gastric cancer." (PMID 40995693, 2025). "In summary, our findings reveal that PITX2 is significantly linked to unfavorable outcomes in gastric cancer and modulates the expression of lysosomal exocytic genes, including MCOLN1 and RAB3A, which enhance the secretion of LGALS1 and IGFBP7." (PMID 40995693, 2025). "In this study, we found that 1‐83 amino acids of HOXA1 was able to interact with N‐terminal transactivation domain of PITX2, resulting in enhanced PITX2 activity to drive transcription of MCOLN1 and RAB3A in gastric cancer cells." (PMID 40995693, 2025). "Compared to their para‐tumoral tissues, higher levels of HOXA1, PITX2, MCOLN1, and RAB3A were observed in gastric cancer specimens." (PMID 40995693, 2025). "Mining the Kaplan‐Meier Plotter database revealed that up‐regulation of MCOLN1 (P = 4.6 × 10−2 and 4.4 × 10−2), RAB3A (P = 7.4 × 10−7 and 5.5 × 10−6), or LAMP1 (P = 3.2 × 10−3 and 2.3 × 10−2) was associated with poor overall or event‐free survival in gastric cancer patients." (PMID 40995693, 2025). "Clinically, elevated expression of HOXA1, PITX2, MCOLN1, RAB3A, LGALS1, and IGFBP7 constitutes a prognostic signature correlating with poor outcomes of gastric cancer patients." (PMID 40995693, 2025). "Mechanistically, HOXA1‐PITX2 complex facilitates the expression of mucolipin 1 (MCOLN1) and RAS‐related protein Rab‐3A (RAB3A), which drive lysosomal exocytosis of galectin‐1 (LGALS1) and insulin like growth factor binding protein 7 (IGFBP7) from senescent gastric cancer cells." (PMID 40995693, 2025). "Since MCOLN1 and RAB3A contribute to Ca2+ release and trafficking essential for lysosomal exocytosis, we further determined whether PITX2 could impact the biological characteristics of senescent gastric cancer cells." (PMID 40995693, 2025).
glioblastoma multiforme (2 papers, 2020 to 2021). "Among the upregulated RAB genes identified in PDAC, a higher expression of RAB3A is also reported in glioblastoma multiforme, where it promotes cell proliferation." (PMID 32759795, 2020).
glioma (2 papers, 2022 to 2025). A benign or malignant brain and spinal cord tumor that arises from glial cells (astrocytes, oligodendrocytes, ependymal cells). "The upregulated RAB3A has been demonstrated that is associated with high-grade gliomas, suggesting an oncogenic role for RAB3A in brain tumors." (PMID 41123819, 2025). "Higher expression levels of RAB3A, SYP, CAMK2A, and GABRA1, as well as lower expression levels of TYROBP and VSIG4, in glioma patients were associated with improved OS and DFS." (PMID 36072978, 2022). "Six hub genes related to glioma diagnosis and prognosis were identified, including RAB3A, TYROBP, SYP, CAMK2A, VSIG4, and GABRA1." (PMID 36072978, 2022). "We identified six hub genes (RAB3A, TYROBP, SYP, CAMK2A, VSIG4, and GABRA1) that predicted the prognosis of glioma." (PMID 36072978, 2022). "After a series of database screening tests, we identified 11 modules during glioma progression, followed by six hub genes (RAB3A, TYROBP, SYP, CAMK2A, VSIG4, and GABRA1) that can predict the prognosis of glioma and were validated in glioma tissues by qRT-PCR." (PMID 36072978, 2022). "Therefore, it could be concluded that RAB3A, TYROBP, SYP, CAMK2A, VSIG4, and GABRA1 may play a critical role in glioma by regulating immune cells." (PMID 36072978, 2022).
Hyperglycemia (2 papers, 2011 to 2024). An increased concentration of glucose in the blood. "The absence of Rab3a in mice was shown to lead to severe hyperglycemia and insulin secretory deficiencies (Varadi, Tsuboi, and Rutter, 2005)." (PMID 38606007, 2024).
lung adenocarcinoma (2 papers, 2023 to 2024). A carcinoma that arises from the lung and is characterized by the presence of malignant glandular epithelial cells. "We found that lncRNA GNAS-AS1 was upregulated, miR-433-3p was low-expressed, and Rab3A was overexpressed in lung adenocarcinoma tissues and cell lines." (PMID 37465347, 2023). "In conclusion, lncRNA GNAS-AS1 downregulation suppressed lung adenocarcinoma cell proliferation and EMT through the miR-433-3p/Rab3A axis." (PMID 37465347, 2023).
lung carcinoma (2 papers, 2015 to 2025). "We selected 6 loci displaying significant differential cirDNA modification in the microarray analysis (Rab3a, Atp6v0c, B4galnt1, Slc1a1, Ttl and Krt15) and whose corresponding genes have been reported as associated to lung cancer phenotypes." (PMID 25415227, 2015). "Protein mass spectrometry experiment, immunoprecipitation, immunofluorescence, subcellular fractionation, mitochondria isolation, cycloheximide assays, and lung cancer xenograft mouse models were performed to clarify the molecular mechanism of RAB3A in NSCLC progression." (PMID 41123819, 2025).
Obesity (2 papers, 2019 to 2023). Accumulation of substantial excess body fat. "PRKCB deficiency reduces the obesity syndrome of mice, while RAB3A is involved in the regulation of insulin secretion." (PMID 37620670, 2023). "MRNA levels of Rap1a and Rap1b were unaffected by diet-induced obesity whereas expression of Rab3a was slightly reduced." (PMID 31337827, 2019).
pancreatic cancer (2 papers, 2022 to 2023). "Another neuroendocrine marker of RAB3A also correlates with better overall survival in pancreatic cancer." (PMID 36713370, 2022).
autism spectrum disorder (1 paper, 2019). A spectrum of developmental disorders that includes autism, and Asperger syndrome. "The SYTL4 gene is known to directly interact with several members of the RAB family of genes, such as, RAB27A, RAB27B, RAB8A, and RAB3A which are known autism spectrum disorder genes." (PMID 31323913, 2019).
chordoma (1 paper, 2025). Chordomas are rare malignant tumors arising from embryonic remnants of the notochord in axial skeleton. "To evaluate the roles of other RAB3 members in the chordoma stemness and tumorigenic functions, we found that RAB3A, RAB3C, and RAB3D regulated the proliferation of CH22 cells, whereas they did not control the expressions of stemness markers, such as TBXT, NANOG, OCT4 and SOX2." (PMID 40135815, 2025).
clear cell carcinomas (1 paper, 2021). "By global mRNA microarray profiling in a total of 196 epithelial OC patients (161 serous, 15 endometrioid, 11 mucinous, and 9 clear cell carcinomas), we found four candidates—HSPA1A, CD99, RAB3A and POM121L9P, which associated with OS and poor clinicopathological features." (PMID 33686173, 2021).
coccidiosis (1 paper, 2025). A parasitic infection caused by Coccidia. "The involvement of Rab proteins, specifically RAB3A and RAB26, in the context of coccidiosis, has not been widely studied." (PMID 41408150, 2025).
cognitive decline (1 paper, 2023). "Data from our exploratory study revealed that both STX1A and Rab3A proteins were differentially expressed in the hippocampus of old samples, allowing us to hypothesize a potential correlation between aging, Aβ aggregates and cognitive decline in cattle." (PMID 37965495, 2023).
cyst (1 paper, 2020). A sac-like closed membranous structure that may be empty or contain fluid or amorphous material. "Together, our results show similar functional requirements of Rab3A, Rab8A, Rab11A and Rab27A compared to what has been previously reported using MDCK cyst models of epithelial lumen formation." (PMID 32569321, 2020).
diabetic nephropathy (1 paper, 2023). "Our findings highlight the Rab3A/Rab27A system as a key participant in podocyte injury and vesicular traffic regulation in diabetic nephropathy." (PMID 37237503, 2023).